CD47 (CD47 molecule)
Diseases named in the same sentence as CD47 in open-access papers (continued):
Sharing a sentence is not in itself a finding about the gene and the disease.
tumor (continued). "In comparison to the control group, the co-targeting of CD47 and VEGF demonstrated effective inhibition of tumor recurrence." (PMID 38532108, 2024). "To assess the impact of CD47 and CD24 signaling on the regulation of macrophage-mediated immune response against cancer, we investigated the expression of CD47 and CD24 in different tumor types." (PMID 38971872, 2024). "Previous studies on the mechanism of action of other CD47 blockade such as CC-90002 and SRF231 also identified increased tumor macrophage infiltration and induction of macrophage cytokines." (PMID 38992659, 2024). "Because CD47 is highly expressed on HCC, AbCD47 can target and block CD47 on the surface of tumor cells to disable the “Don't eat me” signal." (PMID 38520730, 2024). "According to the current paradigm, the interaction between CD47 on tumor cells and SIRPA on macrophages leads to the inhibition of tumor phagocytosis." (PMID 38920727, 2024). "Our study highlights that tumor cell IFN-I responsiveness and the downstream OXPHOS and autophagy pathways are highly required for CD47-SIRPα ICB." (PMID 38982116, 2024). "To explore the effect of Foxp1 on the anti-CD47 Ab regulation of the CTLA4 level, we constructed a subcutaneous transplantation tumor model with Foxp1-deleted LLC cells and wild-type LLC cells, respectively, in mice, and treated them with anti-CD47 Ab." (PMID 38398223, 2024). "Our TMA data supports that tumor cells of patients with late stage disease express high levels of CD36 and CD47." (PMID 39627379, 2024). "When we add anti-CD47 in the combining therapies regimen, this increase in MDSCs reversed, and the MDSC number per gram of tumor decreased." (PMID 36774400, 2023). "Compared with the control group, CD47 CAR-M significantly inhibited the growth of CD47hi A2780 cells and SKOV3 cells-formed tumor." (PMID 37740183, 2023). "Depleting CD47 in GBM cells significantly increases macrophage phagocytosis and inhibits GBM tumor growth, indicating the therapeutic potential of targeting the CD47/SIRPα axis in GBM patients." (PMID 36594466, 2023). "When the β-chains of CD47 and MHC I were simultaneously targeted, anti-tumor activity was significantly enhanced compared to that of CD47 or MHC I alone." (PMID 36911723, 2023). "Experiments in mice showed that the treatment of ATC xenograft mice with anti-CD47 antibody increased TAM frequencies, enhanced expression of macrophage activation markers, enhanced tumor cell phagocytosis, and inhibited tumor growth." (PMID 37007127, 2023). "We also evaluated the cell surface expression of CD47 and CD44 molecules in response to the NaHCO3 and anti-PD-L1 treatments, in a single cell suspension generated from the 4T1-Luc tumor tissues." (PMID 37894298, 2023). "Dedieu’s group engineered a peptide, named TAX2, that targets the interaction between tumor-overexpressed thrombospondin-1 (TSP-1) and CD47." (PMID 37108657, 2023). "CD47, known as integrin-related protein (IAP), is broadly expressed on all cell types, including tumor cells." (PMID 36829496, 2023). "To further develop ICI targeting CD47, we need to better understand the functions of its interactions with TSP1 and SIRPα in the tumor microenvironment." (PMID 36768931, 2023). "A previous study demonstrated that IL-6 generated by TAMs induces upregulation of CD47 on hepatoma cells via the STAT3 signaling pathway, subsequently influencing TAM-mediated phagocytosis, promoting tumor progression in HCC, and leading to poor prognosis." (PMID 37305578, 2023). "In fact, chemotherapy has been shown to induce up-regulation of CD47 and PDL1 expression on tumor cells." (PMID 37468567, 2023). "Another “don’t eat me” signal, the recently discovered CD24/Siglec-10 axis facilitates macrophage infiltration into the tumor by Siglec-10-mediated sensing of CD24 and is complementary to CD47 signaling." (PMID 37822933, 2023).
tumor (continued). "To validate the potential efficacy of blocking CD47 in vivo, we implanted MKN45-luc2-labeled tumor cells into BALB/c nude mouse spleens." (PMID 36860925, 2023). "Here, the authors generate a bispecific lipid nanoparticle targeting CD47 and PD-L1, combined with a STING agonist, to promote anti-tumour immunity." (PMID 36959214, 2023). "In addition, we found changes in the expression of immune checkpoints, including PD-1 and TIGIT on cd47−/− CD8 cells in the tumor microenvironment that could impair their function and suggest crosstalk between CD47 signaling and other immune checkpoint pathways." (PMID 36768931, 2023). "When anti-CD47 and anti-PD-L1 administered simultaneously with both OXP and FOLFOX, it leads to a decrease in tumor Treg content compared to monotherapy with chemotherapeutic agents." (PMID 36774400, 2023). "For instance, they disrupt the CD47-SIRP inhibitory signaling, enhancing macrophage-mediated phagocytosis of tumor cells." (PMID 37822610, 2023). "Tumor cells evade recognition and clearance by immune cells through CD47, whereas LMY1 self-assembled peptide fibrils can block the interaction between CD47 and signal-regulated protein α, thereby activating the phagocytosis of tumor cells by macrophages." (PMID 38069380, 2023). "It effectively suppresses CD47 activation by targeting TSP-1, and reprograms highly vascularized ovarian tumors into poorly angiogenic ones, while concurrently activating anti-tumor immunity." (PMID 36959862, 2023). "A ROS-responsive albumin-based system has been developed to sequentially release antibodies against CD47 and PD1, promoting M1 TAM differentiation and leading to an enhanced anti-tumor response." (PMID 38258072, 2023). "The findings from studies conducted in preclinical models provide strong evidence for the regulatory role of CD47-TSP-1 interactions in angiogenesis and tumor growth." (PMID 38188674, 2023). "Inhibited tumor growth and prolonged survival time of LLC C57BL/6 mice;[94a] facilitated CD47‐based immunotherapy via STING signaling." (PMID 36908053, 2023). "Another study showed that bioinspired hybrid nanoparticles called miR-497/TP-HENPs, formed by CD47-expressed exosomes from SKOV3-CDDP cells and cRGD-modified liposomes, increased drug delivery to target tumor sites by evading MPS clearance." (PMID 37497408, 2023). "CD47 antibody blocks CD47-SIRP interaction, allowing TAM to once again phagocytose tumor cells and halt tumor growth." (PMID 37138860, 2023). "After exploring the pharmacokinetics of ABDC2 in tumor-bearing mice using [89Zr]Zr-DFO-ABDC2, we labeled it with 177Lu for achieving CD47-targeted RIT." (PMID 36939440, 2023). "In the second model, anti-CD47 showed additive effect when combined with T-DM1 and enhanced the anti-tumor activity when combined anti-CD47 + T-DM1 compared to T-DM1 alone or paclitaxel." (PMID 37468567, 2023). "The results of this study demonstrated that OAd-SIRPα-Fc, OAd-Siglec10-Fc and OAd-TIGIT-Fc were able to produce SIRPα-Fc, Siglec10-Fc and TIGIT-Fc, respectively, which effectively bound to CD47+, CD24+ and CD155+ tumor cells." (PMID 38016957, 2023). "Two syngeneic tumor models were used to estimate the in vivo antitumor activity of HER2 CAR-M and CD47 CAR-M." (PMID 37740183, 2023). "“Don’t eat me” axis, e.g., CD47/SIRPα and CD24/Siglec-10 between tumor cells and myeloid cells presents an exciting paradigm for using tumor-induced inhibitory pathways to escape immune surveillance." (PMID 37822933, 2023). "The combination treatment of Abrine and anti-PD-1 antibody has a synergistic effect on suppressing the tumor growth through up-regulating CD4+ or CD8+ T cells, down-regulating the Foxp3+ Treg cells, and inhibiting the expression of IDO1, CD47, and PD-L1." (PMID 37334368, 2023).
tumor (continued). "Regarding the suggested interplay between the two axes CD47:SIRPα and HLA class I:LILRB1 in counteracting effective ADCP of tumor cells as demonstrated for anti-EpCAM or anti-EGFR antibodies, additional antibody combinations were studied." (PMID 37781391, 2023). "Next, examination of the tumor cell membranes, using WB analysis after nanoparticle encapsulation, detected the proteins EGFR and CD47, specific for OCM and PLM, on the hybrid membrane and [Dbait-ADM@ZIF-8]OPM." (PMID 36873373, 2023). "By competing with CD47 on the tumour cell surface for the binding of CD47/SIRP on phagocytes, the nanovesicles overexpressing CD47 increased the phagocytosis rate of tumour cells by macrophages." (PMID 37735659, 2023). "In addition, oncogenic MYC signaling could overexpress CD47 and PD-L1 on tumor cells." (PMID 37546397, 2023). "In a more comprehensive BC analysis, including 100 early and 98 metastatic BC patients, a low concordance between PD-L1 and CD47 on CTC and tumor tissue as well as on peripheral blood mononuclear cells and tumor-infiltrating lymphocytes was observed." (PMID 35366112, 2023). "In tumor-bearing mice, only FOLFOX induced an increase in the CD47 expression, and even while OXP treatment increased CD47 expression on CT-26 cells surface, this increase was insignificant." (PMID 36774400, 2023). "Combining blocking antibodies against CD47 and PD-L1 with FOLFOX leads to a significant increase in survival and a decrease in tumor size." (PMID 36774400, 2023). "Another interesting result is that MyxV_CD47, contrary to our expectations, evoked more CD4+ T-cells than MyxV_IFN-γ, and even increased the IFN-γ+ CD4+T-cell population in the tumor." (PMID 37835397, 2023). "β-catenin promotes tumour development by regulating the expression of immune escape-related molecules (CCL4, CD47 and PD-L1) through transcription factors (MYC, TCF/LEF, NF-κβ, SNAI1, etc.)." (PMID 36646807, 2023). "Furthermore, CD47 inhibition could also inhibit proliferation and induce apoptosis of tumour cells." (PMID 37974395, 2023). "Within the dynamic tumor microenvironment, a subpopulation of mesenchymal tumor cells, known as Circulating Cancer Stem Cells (CCSCs), express markers like CD133, TrkB, and CD47, making them radioresistant and pivotal to metastasis." (PMID 38033871, 2023). "Encouragingly, when an anti‐CD47 antibody was added, the effects of the CAR‐MΦ‐mediated in vivo tumor phagocytosis and induced adaptive immunity were further boosted, leading to robust tumor control and prolonging the survival time of all animals to >120 days." (PMID 37906032, 2023). "Promising results were obtained with combinations of LILRB1-directed antibodies and tumor targeting antibodies, bispecific CD3 antibodies or other immune checkpoint inhibitors blocking CD47 or PD-1." (PMID 37781391, 2023). "Dual targeting of both innate and adaptive checkpoints is theoretically attractive, also since data suggest that dual targeting of discrete checkpoints, e.g. CD47, PD1/PD-L1 or CTLA4, can be synergistic with regard to their anti-tumor effects." (PMID 37012357, 2023). "For example, tumor-promoting TAMs can be reprogrammed into tumor-suppressor TAMs by PI3K-γ suppressors, CD40 agonists, anti-CD47 antibodies, and class-IIa HDAC suppressors." (PMID 37915049, 2023). "Many studies have confirmed that blocking CD47 interaction with SIRPα can enhance cancer cell clearance via macrophage inhibition of CD47/SIRPα interaction, which may increase antigen cross-presentation, leading to an adaptive anti-tumor immune response with T-cell priming." (PMID 38136311, 2023). "By choosing Nbs that exclusively bind the D1 domain of hSIRPα, we were able to identify binders that selectively block the interaction with CD47 and enhance ADCP in combination with the tumor-opsonizing antibody cetuximab in vitro." (PMID 38164132, 2023).
tumor (continued). "In the PDX model, combined anti-CD47 synergized with T-DM1 and significantly enhanced the anti-tumor activity of the combined regimen combined to monotherapy and control." (PMID 37468567, 2023). "In recent studies, CD47/SIPR-α blockade led to an increase in CD8+ Tcells frequency and function in the tumor microenvironment." (PMID 36774400, 2023). "Control groups included tumor-bearing animals treated with BSH + BNCT, CD47 knockdown alone, and neutron irradiation alone." (PMID 37408232, 2023). "Our data revealed that in CT-26 tumor-bearing mice, FOLFOX in a combination of anti-CD47 and anti-PD-L1 resulted in a significant increase in survival and reduction in tumor size." (PMID 36774400, 2023). "The CD47/SIRP-α pathway is crucial for tumour immune escape, and blocking it enhances macrophages immune killing against tumours." (PMID 37965573, 2023). "To define an appropriate human tumor model for further studies, we evaluated several NHL cell lines and found CD47 to be highly expressed by these cells." (PMID 37781520, 2023). "Magrolimab is an anti-CD47 antibody that induces tumor phagocytosis and eliminates LSCs in AML preclinical models through CD47 blockade." (PMID 38137469, 2023). "Combination therapies that target both CD47 and other immune checkpoints, such as PD-1 and CTLA-4, are also being studied to enhance anti-tumor immunity." (PMID 38188674, 2023). "In terms of immune checkpoints, the expressions of CTLA4, CD276, CD47 and TNFRSF25 were significantly higher in “stiff tumor”." (PMID 37179366, 2023). "THBS1 and CD47 also jointly participate in anti-tumor immunosuppressive effects, where upregulated expression of THBS1-CD47 not only accelerates the progression of EMT, but also induces fibrosis and inflammation." (PMID 37905960, 2023). "CD47-targeted therapies, including antibody-based therapies, CAR T-cell therapy, and combination therapies, have shown promise in enhancing anti-tumor immunity and improving clinical outcomes." (PMID 38188674, 2023). "This pathway can stimulate the expression of immune checkpoint genes, such as CD47 and PDL1, which facilitate tumor immune evasion." (PMID 37790933, 2023). "In preclinical models of LMS, an anti-CD47 monoclonal antibody demonstrates increased phagocytic activity of LMS cells, thus inhibiting tumor growth and metastatic spread." (PMID 36969049, 2023). "Blocking the interaction between CD47 and macrophage SIRPα increases cytosolic DNA sensing and activates the STING pathway activation that enables detection of tumor mitochondrial DNA and subsequent antigen presentation to T cells." (PMID 37822933, 2023). "Blocking CD47 promotes macrophage phagocytosis in ATC cell lines and inhibits tumor growth in vitro." (PMID 37007127, 2023). "Blockade of the CD47/SIRPa pathway can enhance macrophage-mediated phagocytosis (MMP), increase the frequency of TAMs in TME, and reduce tumor growth." (PMID 36761751, 2023). "The expression profile of CD47 was significantly higher in the WNT compared to the other subgroups and non-tumor tissue." (PMID 36825029, 2023). "CSCs express CD47, CTLA4, PD-L1, TIM-3 and LAG3, which promote immune evasion in the malignant environment and maintain tumor survival." (PMID 36810098, 2023). "Blockade of the CD47-SIRPα interaction is a promising TAM-directed therapeutic approach, with the aim of promoting ADCP of tumor cells by macrophages." (PMID 38162643, 2023). "Tumor size analysis also showed that mice receiving anti-CD47, anti-PD-L1, and FOLFOX had the slowest tumor growth rate." (PMID 36774400, 2023). "For instance, TAMs can promote the evasion of tumor cells from immune surveillance through both typical mechanisms of MCSF-CSF1R and CD47-SIRPα." (PMID 36451865, 2022). "Taken together, the tumour antigens MSLN, CD70, EGFR and HER2 are being exploited as targets for target‐selective CD47 blockade for solid cancer with preclinical proof‐of‐concept for enhanced selectivity and activity." (PMID 35908284, 2022).
tumor (continued). "Among those immune checkpoint genes, both CD47 and SIRPA were remarkably upregulated in the hot tumor group." (PMID 35211415, 2022). "Studies have shown that blocking the expression of CD47 on the surface of tumor cells or the CCR5 receptor expressed by the microglia in GBM can both effectively increase the ratio of M1/M2 and enhance tumor phagocytosis." (PMID 36159398, 2022). "Chemotherapy with an OXA prodrug, PDT via a PEGylated photosensitizer, and immunotherapy via CD47 blockade not only efficiently regressed primary and distant tumors, but also prevented autologous tumor recurrence in both CT26 and 4T1 tumor models." (PMID 35652198, 2022). "Another antibody targeting CD47 has been used after surgical resection of GBM in rats and extended survival of the animals and retarded relapse of the tumor has been observed." (PMID 35214076, 2022). "Our results further showed that DSF/Cu and anti-CD47 combination therapy enhanced the activation of DCs and CD8+ T cells in the tumor microenvironment and improved antitumor response." (PMID 36230638, 2022). "Therapeutic inhibition of CD47 using specific antibodies in preclinical orthotopic models of solid tumors, including GBM, showed a decrease in tumor growth increasing animal survival." (PMID 36186781, 2022). "Because c-MYC can directly bind to the CD-47 and PD-L1 gene promoters, inhibiting c-MYC reduces the expression of both genes (CD-47 and PD-L1) and thus improves the anti-tumor immune response." (PMID 37305016, 2022). "Gene Expression Omnibus (GEO) dataset analysis showed that CD47 expression positively correlates with M1 marker CD80 and M1 abundance in tumor-infiltrating immune cells." (PMID 36274066, 2022). "The elevated expression of CD47 in cancers prevents macrophage phagocytosis and the anti-human CD47 antibody B6H12 prevents tumor growth in several xenograft models by preventing SIRPα engagement." (PMID 36233088, 2022). "The regulation of CD47 on CD8+ T cell phenotype and function is context-dependent, as evident by the distinct activation patterns of splenic and tumor-infiltrating CD8+ T cells of the same animal." (PMID 36105746, 2022). "Because the potent role of CD47/SIRP-alpha signaling in suppression of macrophage phagocytosis, blocking the CD47/SIRP-alpha interaction between macrophages and tumor cells has become a promising approach in cancer immunotherapy." (PMID 35634325, 2022). "After analyzing the tumor infiltrating CD8+ T cells, we found significant reductions of PD1, CD39, and TIGIT levels in Cd47−/− mice." (PMID 36105746, 2022). "CD47 was consistently highly expressed in tumor samples of CHOL, COAD, ESCA, HNSC, KIRC, STAD, THCA, and consistently low expressed in tumor samples of LUSC than normal tissues in both comparisons." (PMID 35697717, 2022). "CD47 expression was decreased in tumor tissue in LUSC, predicting better OS; CD47 expression was increased in tumor tissue in THCA, predicting better OS." (PMID 36059952, 2022). "Zhou and colleagues found that CD47 blockade and ICD induction efficiently boosted antitumor immunity and inhibited the tumor growth." (PMID 36230638, 2022). "Here, a nanotechnology approach is reported for tumor homologous targeting via CD9 and phagocytosis escape via CD47 through UE−coated poly (2−ethyl−2−oxazoline)−poly (D, L−lactide) (PEOz−PLA) nanoparticles (UEPP NPs)." (PMID 36004889, 2022). "The study showed that HX009 blocked both CD47/SIRPα and PD-1/PDL-1 interactions, and interacted with CD47 on tumor cells and PD1 on T cells to help present tumor antigens to T cells, resulting in activation of the innate and acquired immune responses." (PMID 35418166, 2022). "Together, these existing studies have confirmed that a combined anti-CD47/SIRPα and anti-PD1/PDL1 strategy enhances the anti-tumor activity among some solid tumors." (PMID 35317832, 2022).